ATF4 (activating transcription factor 4)
Diseases named in the same sentence as ATF4 in open-access papers (continued):
Sharing a sentence is not in itself a finding about the gene and the disease.
tumor (continued). "Previous reports highlight an essential role for ATF4 in CD8+ T-cell survival and tumor control, particularly under conditions of asparagine scarcity, which promotes CD8+ T-cell proliferation and fitness via ATF4-mediated metabolic rewiring." (PMID 40335738, 2025). "PERK/eIF2α/ATF4 activation is correlated with GBM progression from grade III to grade IV, while rat tumor xenografts exhibit hyperactive PERK in comparison to normal rat brain samples." (PMID 40563622, 2025). "UPR sensors, such as ATF4, upregulate the expression of the antiapoptotic genes BCL-2 and FLIP and protect tumour cells against apoptosis in response to drug-induced stress, leading to tumour cell resistance to chemotherapeutic drugs." (PMID 38297380, 2024). "The combination of RY103 and sunitinib significantly downregulated the protein expressions of CD34 and ATF4, indicating an effective blockage of the GCN2 pathway and thus suppression of tumor angiogenesis." (PMID 39065567, 2024). "In triptolide-treated tumor cells, the expression levels of GRP78, phosphorylated eIF2α, ATF4, and CHOP were elevated, indicating that triptolide activates the eIF2α/ATF4/CHOP axis—an essential branch of the ER stress-mediated apoptosis pathway." (PMID 39770441, 2024). "This stress response stabilizes the transcription factor NRF2, and, in various cell lines and tumor models, NRF2 and ATF4 are reported to function cooperatively, reinforcing responses to amino acid limitation and oxidative stress." (PMID 39131293, 2024). "Recently, ATF4 has been shown to promote amino acid biosynthesis and tumor cell survival in PDAC while eIF2α phosphorylation significantly correlates with tumor recurrence/metastasis and shorter overall survival." (PMID 37645713, 2024). "A recent report showed that in melanoma and pancreatic tumors ATF4 is also important for fibroblast activation, and its knockout inhibits CAF-mediated development of tumor vasculature and tumor growth and metastasis." (PMID 38455762, 2024). "As expected, we observed an increase in ATF4 and GADD34 mRNA levels in skeletal muscle, however only GADD34 was elevated in the heart of tumor‐bearing rats." (PMID 39294861, 2024). "ER stress is mainly manifested by accumulation of misfolded and unfolded proteins, which can promote antioxidant reaction through ATF4 and NRF2, reducing oxidative stress and promoting tumor metastasis." (PMID 38685045, 2024). "FAM129A is a downstream molecule of activating transcription factor 4 (ATF4) and is known to inhibit apoptosis and promote tumor cell migration and proliferation." (PMID 39123740, 2024). "In IDO1-SOE mice, serum KP activity and VEGFA concentration were increased accompanied by a rise in the expression of CD34, ATF4, IDO1, and VEGFA in tumor tissues, with the most significant uplift observed in ATF4 and IDO1 expression." (PMID 39065567, 2024). "Further research indicated that in neuroblastoma, fenretinide achieves its anti-tumor effects by inducing ERS, specifically through upregulating ATF4 transcription levels, thereby promoting apoptosis." (PMID 39080273, 2024). "Immunohistochemical staining of ATF4 and SPHK1 was further studied in the micro-sections of tumor tissues." (PMID 39090107, 2024). "Upregulated ATF4 and SLC1A5 expressions are observed in tumor tissue, which is positively correlated with the tumor, node, and metastasis (TNM) stages." (PMID 39696988, 2024). "Oridonin (Compound 8), a diterpenoid compound with anti-tumor potential extracted from Rabdosia rubescens, has been demonstrated to trigger ER stress in CRC cells, as evidenced by increased levels of ATF4 and CHOP proteins." (PMID 39770441, 2024).
tumor (continued). "Activating transcription factor 4 (ATF4) is an essential link between ER stress and oxidative damage, contributing to ferroptosis in a tumor-type-dependent manner mediated by a signal pathway such as ATF4–HSPA5–GPX4." (PMID 36627482, 2023). "Our results revealed that the levels of GRP78, ATF4, CHOP, p‐IRE, and XBP1 expression were increased in mouse tumour tissue overexpressing USP19, indicating an increased ER stress parallel to the expression of USP19 in TNBC tumorigenesis." (PMID 37700495, 2023). "Glutaminolysis blockade enhanced FTO expression and disrupted YTHDF2-mediated RNA decay of activating transcription factor 4 (ATF4), stimulating autophagy activation and compromising anti-tumour efficacy." (PMID 36859310, 2023). "GOLGA2P10 is frequently upregulated in HCC tissues, induced by PERK/ATF4/CHOP signaling, and protects tumor cells from ER stress-induced apoptosis by regulating members of the Bcl-2 family of antiapoptotic proteins." (PMID 37790807, 2023). "As in young DEN-challenged mice, ATF4 ablation enhanced HCC development, and compared with AAV8-mCherry transduction, AAV8-xCT transduction significantly reduced both tumour number and tumour size." (PMID 36996941, 2023). "Based on the TCGA database, we compared the mRNA expression of PDIA4, ATF4, SLC7A11, and PERK between RCC tumor and adjacent normal tissue." (PMID 36906674, 2023). "The result of the analysis revealed the expressional level of PDIA4, ATF4, and SLC7A11 in the RCC tumor is higher than the one in the adjacent normal tissue, respectively." (PMID 36906674, 2023). "Single-cell RNAseq and clustering analysis of these tumours uncovered a significant downregulation of CAF markers, such as Acta2 and Pdgfrb, in the CAF component of ATF4 knockout mice." (PMID 36765657, 2023). "Experimental evidence has shown that the knockdown of PERK and ATF4 in breast cancer (MCF7) and HNSCC cell lines (UM‐SCC‐81B) can slow tumour growth and reduce tumour vascular density." (PMID 36852470, 2023). "Bioinformatical analyses based on clinical tumor samples and database indicated a positive correlation exists between PDIA4 and PERK/ATF4/SLC7A11 signaling pathway, as well as the malignant prognosis of RCCs." (PMID 36906674, 2023). "MCC1734 possibly exerts antitumor effects by upregulating the p-PERK, eIF2α, ATF4, and CHOP proapoptotic pathways in tumor cells." (PMID 37790807, 2023). "Among the main responses of UPR, the IRE1α-XBP1 and PERK/eIF2α/ATF4 pathways play critical roles in TNBC, such as tumor initiation, vascularization, progression, and tumor microenvironment reprogramming." (PMID 37540709, 2023). "The deletion of ATF4 alone, a single downstream ISR target, has been successful in significantly slowing MYC-driven tumor progression that relies on both GCN2 and PERK signaling in lymphomas." (PMID 37601686, 2023). "The protein expression of p-PERK, ATF4 and CHOP in mouse tumor tissues was evaluated, and the KGM+5-FU-induced elevation in the protein levels of p-PERK, ATF4 and CHOP was reversed after TLR4 upregulation." (PMID 37304412, 2022). "Targeted inhibition of ATF4 impedes progression of MYC-driven cancers, emphasizing the important role of this ISR effector in tumor progression." (PMID 36107759, 2022). "To investigate if the differential expression of the ATF4 pathway was retained in isolated human PDA cells, we established a set of clonal cell lines derived from a human PDA tumor." (PMID 36411320, 2022). "The WWTR1–ASNS network, ATF4–ASNS network, and DDIT3–ASNS network are reported to inhibit the proliferation and tumor formation of cancer cells." (PMID 35625787, 2022). "Activation of the GCN2/ATF4 pathway in cancer cells promotes tumorigenesis, while targeted deletion of ATF4 and/or GCN2 resulted in apoptosis and tumor regression." (PMID 34994382, 2022). "The results showed that FOD can significantly increase the expression levels of p-PERK, p-EIF2α, ATF4 and CHOP in tumor tissues of FOD group compared with model group." (PMID 36523497, 2022).
tumor (continued). "Significantly, western blot analysis of tumor tissue confirmed that DAS markedly up-regulated the expression levels of p27, p21, p-eIF2α, ATF4, DR5, Noxa, and cleaved PARP compared with control, which was consistent with in vitro experiments." (PMID 35965681, 2022). "All three branches (through ATF4, XBP1s and ATF6) can directly bind to the promoter of VEGFA and other proangiogenic genes to alleviate tumor hypoxia." (PMID 36139473, 2022). "Our findings also reveal that in tumor spheroids, which more closely mimic the properties of solid tumors, cFLIPL levels remained high during ER stress despite activation of the PERK/ATF4/CHOP branch of the UPR and up-regulation of TRAIL-R2/DR5 expression." (PMID 35115486, 2022). "In the breast cancer mouse model, exogenous and tumor-derived OPN can promote VEGF expression and tumor angiogenesis by activating the Brk/NF-κB/ATF-4 signaling pathway." (PMID 35898884, 2022). "Together, these findings suggest that ATF4-dependent activation of CAFs dictates early ECM organization and CAF-instructed angiogenesis to support the growth of primary tumours and the metastatic phenotype." (PMID 35654839, 2022). "Compared with the aCtrl and bCtrl groups, the mRNA and protein expression levels of ATF4, DDIT3 and IκBα in tumour were significantly increased in all SNP‐related groups (p < 0.05), except for ATF4 protein expression in the bSNP‐50 group (p > 0.05)." (PMID 34302428, 2021). "We also validated significantly upregulated expression of ER‐stress markers GRP78, ATF4, CHOP and apoptosis marker BIP, BIM, cleaved caspase 3 in the tumour xenografts with HCN2 or HCN3 knockdown." (PMID 34841695, 2021). "Both low and high proliferative luminal tumours showed weak positive correlation between GLS2 protein and ALDH18A1 (p < 0.001), ALDH4A1 (p < 0.01), ATF4 (p = 0.001), PRODH (p < 0.001), SLC38A2 (p ≤ 0.001) and SLC7A11 (p < 0.001)." (PMID 34439127, 2021). "Immunohistochemical staining was used to evaluate the expression levels of Ki-67, ATF4, and CHOP in tumor tissue." (PMID 34306318, 2021). "To examine the ATF-4 response, we measured the expression of the two ATF-4 targets, PHGDH and PSAT1, in DLD-1 tumours." (PMID 33446657, 2021). "As a result, loss of p62 in the CAFs supports prostate cancer growth in a mouse model through ATF4-ASNS axis, likely by facilitating tumor cell adaptation to glutamine-limiting environment." (PMID 34205460, 2021). "The UPRmt axis, including SIRT3, PERK, CHOP, ATF4/5, ETC pathways, mainly aggravates the tumor progression." (PMID 34717757, 2021). "ATF4 knockdown as well as inhibition of the ISR sensitized hLcn-2-treated renal tumor cells to ferroptosis, thus linking the ISR to pro-tumor characteristics of hLcn-2." (PMID 34069743, 2021). "FAM129A, a molecule downstream of activating transcription factor 4 (ATF4), inhibits apoptosis and promotes tumor cell migration and proliferation in various cancers." (PMID 34150610, 2021). "In contrast, the expression levels of ATF4 and CHOP were elevated in tumor tissue after NTPAM treatment." (PMID 34306318, 2021). "Recently, the same group found that the ability of asparagine to activate mTORC1 represents a key adaptive strategy for tumor cells to mitigate ETC inhibition-induced stress, which is coupled to ATF4 activation." (PMID 34205460, 2021). "The integrated stress response mediators ATF4 and ATF3 have been known to impact tumor cell survival in part through regulation of the Bcl-2 family members of proteins." (PMID 32664214, 2020). "NK_c3 and NK_c5 were mainly derived from non-tumor liver tissues (23.57% and 5.97%, respectively) and characterized by high expression of transcription factors such as FOS, FOSB, FOXP1, and ATF4, and two genes involved in the NF-κB pathway, NFKBIA and NFKBIZ." (PMID 33298893, 2020). "We analyzed CDK4, CDK6, cyclin A, cyclin D1, ATF4, and CHOP protein levels in excised tumor sections from saline- and CPX-treated groups." (PMID 32719342, 2020).
tumor (continued). "Our findings demonstrated that ONC206 increased the expression of ER stress-related proteins including ATF4, PERK, and Bip, and significantly inhibited tumor cell migration and invasion in vitro." (PMID 33194693, 2020). "For example, gene deletion of the protein kinase R (PKR)-like ER kinase (PERK) target activating transcription factor 4 (ATF4) inhibits pro-survival adaptations to cell stress and leads to regression of tumor growth." (PMID 31779147, 2019). "The knockdown of ATF4, or the suppression of its induction by GCN2 silencing, inhibited tumor growth in vivo." (PMID 31998641, 2019). "It has been reported that PERK/eIF2alpha/ATF4 activation during UPR increases tolerance to extreme hypoxia and promotes tumor growth under hypoxia condition." (PMID 31395860, 2019). "In human tumour tissues, and several tumour cell lines, blocking UPR by silencing PERK or ATF4 significantly reduces the production of angiogenesis mediators induced by glucose deprivation." (PMID 31071975, 2019). "The protein levels of IRF1, eIF2α, ATF4, and PDL1 in the tumor tissues of the all subject group were significantly correlated with each other and formed a cluster in dendrogram." (PMID 30305853, 2018). "The protein levels of IRF1, eIF2α, ATF4, and PDL1 in the tumor tissues of the all subject group formed a cluster in the hierarchical cluster dendrograms." (PMID 30305853, 2018). "The protein levels of ATF4 and PDL1 had the closest proximity in both tissues, and they formed a cluster with those of IRF1, eIF2α, and IFNAR1 in the tumor tissue." (PMID 30305853, 2018). "Significant correlations among the protein levels of PDL1, eIF2α, and ATF4 and between those of IRF1 and PDL1 were observed in the tumor tissues of both subgroups and in the normal tissue of SCC." (PMID 30305853, 2018). "There was a positive relationship between SLC7A5 and MYC, mTOR and ATF4 (p < 0.001) and the positive relationship between MYC, HIF2A and SLC7A5 was only observed in luminal B tumours (p = 0.01 and p < 0.001, respectively)." (PMID 29566741, 2018). "Re‐analysis of these key molecules in tumour tissues indicated that phosphor‐eIF2α, ATF3 and ATF4 were remarkably induced in TSA‐treated mice, in agreement with the results observed in cultured cells." (PMID 29327812, 2018). "In this study, we showed that PlGF inhibition reduced tumour hypoxia and PERK activation in vivo and that hypoxia activates the PERK/phospho-IF2α/ATF4 cascade in HCC cells, suggesting that tumour hypoxia mediates the observed PERK activation in HCC." (PMID 26753564, 2016). "Supporting potential tumor suppressive function for the UPR, HRAS-dependent transformation of primary human melanocytes was potentiated by genetic inhibition of PERK, Ire1 and ATF4." (PMID 27977682, 2016). "SIAH2 was shown to lead to LATS2 destabilization and YAP activation in hypoxic cells, an effect that provides a tentative connection between ATF4 and HIPPO pathway in stressed cells in the tumor microenvironment." (PMID 27409837, 2016). "Mitochondrial rpL41 targets the activating transcription factor 4 (ATF4), a major regulator of tumor cell survival, for degradation contributing to sensitize tumor cells to chemotherapy." (PMID 27835895, 2016). "Activating transcription factor 4 (ATF4), a member of the ATF/CREB family, has been reported to be related to tumor angiogenesis." (PMID 25883982, 2015). "Mechanistically, it has been shown that tumor hypoxia induces unfolded protein response (UPR) pathway, which in turn induces LAMP3 via the PKR-like ER kinase (PERK)/activating transcription factor 4 (ATF4)-arm of the UPR." (PMID 25362357, 2014).
tumor (continued). "The linkage between ATF4 expression level and FAZA retention was weak to modest with substantial tumor-to-tumor variability, but the positive correlation in SCCVII tumors was significant in two out of four tumors and when all data were pooled." (PMID 21306648, 2011). "However, ATF4 and its upstream regulator GNC2 are also crucial for CD8+ T-cell survival and antitumour activity within the tumor microenvironment, highlighting its paradoxical role in immune regulation." (PMID 40335738, 2025). "Paradoxically, chronic ER stress-induced ATF4 hyperactivation may upregulate pro-apoptotic factors like CHOP, suggesting context-dependent tumor-suppressive potential." (PMID 40265021, 2025). "Among them, TR57 inhibits the growth and proliferation of SUM159 tumor cells of breast cancer by inducing ISR and endoplasmic reticulum stress response marker ATF4 and CHOP protein expression levels, inhibiting TFAM and TuFM protein expression levels, and inhibiting colony formation ability." (PMID 40395852, 2025). "Furthermore, in NSCLC, Celecoxib promotes ATF4 expression by upregulating Inc-HFE2-2:1, thereby activating the ER stress to enhance tumor cell apoptosis." (PMID 40777108, 2025). "Furthermore, the combination drug decreased the mRNA expression levels of downstream c-Myc targets, including CDK4, PABPC1, ATF4, BCL2L12, and HMGA 31, in MDA-MB-231 and BT-549 cells, which are important effectors of c-Myc inhibition-induced tumor suppression." (PMID 41281757, 2025). "Meanwhile, we revealed that HBV G1896A mutation‐induced ER stress could promote glycolysis through the ATF4‐PFKFB3 axis, which contributed to HCC tumor growth, metastasis and exacerbates the prognosis of HCC." (PMID 40919132, 2025). "In RMS, both the HSP70 (heat shock 70 kDa protein) inhibitor MAL3-101 and the p97 (valosin containing protein) ATPase inhibitor CB-5083 trigger robust UPR activation, marked by increased eIF2α phosphorylation, ATF4 and CHOP upregulation, and XBP1 splicing, thereby promoting tumor cell death." (PMID 41228282, 2025). "Using UPR inhibitors and in loss-of-function experiments for transcription factors such as, XBP1, ATF4 and ATF6, we find that C5aR1 expression is complementarily regulated by multiple UPR pathways; highlighting the strong dependence of tumour cells on UPR-dependent C5aR1 signalling." (PMID 40695778, 2025). "Furthermore, bavachin activated the endoplasmic reticulum stress pathway as evidenced by upregulation of GRP78, ATF4, PERK, and CHOP, and notably inhibited phosphorylation of ERK1/2 and p38 MAPK signaling pathways essential for tumor cells survival." (PMID 40599869, 2025). "Tumor microenvironmental stresses, including hypoxia and nutrient limitation, trigger Gln starvation-induced endoplasmic reticulum stress, leading to GCN2-mediated phosphorylation of eIF2α and upregulation of ATF4." (PMID 40830338, 2025). "Interestingly, we determined that the transcription factor ATF4, which is highly expressed in various tumors, acts inversely on the promoter region of KYNU in tumor cells, resulting in an excess of KYNU in the TME." (PMID 40616124, 2025). "Additionally, LUAD cell lines and orthotopic tumor xenografts have been employed to study ATF4 activation of LINC00958, validating its contribution to immune escape and tumor progression." (PMID 40777108, 2025). "Notably, ATF4 overexpression upregulated the levels of KYNU in ECCs/ECSCs, indicating that ATF4 affects KYNU production by tumor cells." (PMID 40616124, 2025). "Although GSK414 impaired ATF4 expression, it did not affect tumor cells proliferation when used as a single agent." (PMID 40667288, 2025). "Furthermore, TMTC3 activates the PERK pathway, leading to the nuclear translocation of ATF4, which induces EMT and accelerates tumor cell growth and metastasis." (PMID 40302812, 2025).